TRAF4 (TNF receptor associated factor 4)
Diseases named in the same sentence as TRAF4 in open-access papers (continued):
Sharing a sentence is not in itself a finding about the gene and the disease.
breast carcinoma (continued). "In line with a previous comparative genomic hybridization study, female breast cancer showed more frequent amplification in a variety of genes, particularly in TRAF4 and EMSY." (PMID 22527098, 2012). "TRAF4 mRNA was shown to be overexpressed in approximately one-quarter of breast cancers as a consequence of gene amplification." (PMID 24212830, 2011). "TRAF4 was initially identified in breast cancer from a differential screen between metastatic lymph nodes and benign fibrodenomas biopsies." (PMID 24212830, 2011). "In contrast, TRAF4 interacts with phosphoinositides (PIPs) to drive breast cancer." (PMID 36625999, 2023). "We also determined HER2 and TRAF4 expression in eight breast cancer cell lines." (PMID 35864174, 2022). "Girdin is mainly expressed in the cytoplasm of breast cancer cells, but TRAF4 could facilitate its translocation from the cytoplasm to the nucleus." (PMID 35242717, 2022). "Breast cancer cells overexpressing TRAF4 were more resistant to stress-induced death." (PMID 35242717, 2022). "Correlation between TRAF4 and Eg5 protein level in breast cancer tissue." (PMID 35692762, 2022). "In addition, through TNF-α signaling, TRAF4 exerts anti-apoptotic effects on breast cancer and osteosarcoma." (PMID 35242717, 2022). "TRAF4 protein was discovered in breast cancer-derived metastatic lymph nodes." (PMID 35692762, 2022). "TRAF2 and TRAF4 proteins were co-localised in two breast cancer cell lines, MCF-7 and MDA-MB231." (PMID 35242717, 2022). "Furthermore, TRAF4 knockdown decreased HER2 expression in four HER2+ breast cancer cell lines while enhancing Trastuzumab sensitivity." (PMID 35864174, 2022). "TRAF4 promotes the proliferation of breast cancer cells by enhancing β-catenin expression." (PMID 35242717, 2022). "TRAF4 is essential for migrating normal breast epithelial cells and breast cancer cells." (PMID 35242717, 2022). "TRAF4 was initially identified in human breast cancer in 1995." (PMID 35748027, 2022). "TRAF4 is an E3 ubiquitin ligase that is overexpressed in breast carcinoma." (PMID 33991522, 2021). "Moreover, the tumor-facilitator role of TRAF4 has been validated in hepatocellular carcinoma, intrahepatic cholangiocarcinoma, breast cancer, and colon cancer." (PMID 32280300, 2020). "TRAF4 is expressed in the nucleus and is correlated with poor prognosis in breast cancer patients." (PMID 29343747, 2018). "The nuclear expression of TRAF4 is correlated with poor survival in breast cancer patients." (PMID 28774312, 2017). "Interestingly, it has been reported recently that high TRAF4 nuclear expression is also correlated with poor survival in breast cancer patients." (PMID 25738361, 2015). "TRAF4 was predominantly positively immunostained in the nucleus of normal breast epithelial cells, while besides the nuclear stain, the cytoplasm expression of TRAF4 was obviously found in breast cancer cells." (PMID 25738361, 2015). "This indicated the localization of TRAF4 in the cytoplasm may contribute to the progression of breast cancer." (PMID 25738361, 2015). "In summary, the overexpression of TRAF4 indicates poor survival of breast cancer patients." (PMID 25738361, 2015). "To confirm whether the interaction between TRAF4 and p70s6k only occurred in specific cells, we tested breast cancer cells MCF7 and MDA-MB-231." (PMID 25738361, 2015). "The results of the present study in breast cancer cells and human breast tissues may indicate that TRAF4 has an important role in breast cancer." (PMID 24396457, 2014). "In addition, TRAF4 expression in the estrogen receptor-positive breast cancer cell lines was higher than in the estrogen receptor-negative breast cancer cell lines." (PMID 24396457, 2014). "Future studies must clarify the roles of TRAF4 in apoptotic reactions and may contribute to the development of a new strategy against breast cancer." (PMID 24396457, 2014).
breast carcinoma (continued). "Our results suggest that TRAF4 overexpression might contribute to breast cancer progression by destabilizing TJs and favoring cell migration." (PMID 24311986, 2013). "Therefore, gain of TRAF4 function appears to be an important factor for the development and progression of breast cancer." (PMID 24311986, 2013). "Given that TRAF4 is overexpressed in breast cancer and that migration of cancer cells participates in tumor progression, we addressed the role of TRAF4 in the migration of breast cancer cells." (PMID 24311986, 2013). "Moreover, they show that TRAF4 acts as a negative regulator of TJs and favors migration of breast cancer cells." (PMID 24311986, 2013). "TRAF4 expression is altered in breast carcinomas and the protein shifts from TJs to other subcellular territories, suggesting that it could be part of the mechanisms leading to the disruption of the polarized breast epithelium." (PMID 24311986, 2013). "Notably, TRAF4 was found to be overexpressed through gene amplification in about 20% of breast cancers." (PMID 24311986, 2013). "Analysis of data from 212 patients collected from 2 pooled studies showed that high expression of TRAF6, not TRAF4, is associated with poor survival rate in breast cancer patients over a 5-year period (Log Hazard Ratio [HR]:1.01, 95% CI: 1.01, 1.01, P < 0.00001)." (PMID 36944688, 2023). "In addition, TRAF4 activates TGF-β receptor signaling to accelerate breast cancer metastasis." (PMID 36625999, 2023). "By studying the relationship between TRAF4 and Eg5, a member of the kinesin family that plays a critical role in spindle assembly, we demonstrated that TRAF4 regulated Eg5 ubiquitination and contributed to Eg5-mediated breast cancer proliferation and inhibited breast cancer apoptosis." (PMID 35692762, 2022). "TRAF4 may promote breast cancer progression by altering the expression of cell nucleus." (PMID 35242717, 2022). "Therefore, TRAF4 KD/KO enhanced Trastuzumab sensitivity in resistant HER2+ breast cancer cells." (PMID 35864174, 2022). "Cytoplasmic expression of TRAF4 may be a new potential marker of breast cancer cell migration." (PMID 35242717, 2022). "Moreover, TRAF4 has been found to be amplified during breast cancer progression." (PMID 33804427, 2021). "So, TRAF4 may promote the proliferation of breast cancer cell through p70s6k/S6 signaling pathway." (PMID 25738361, 2015). "In the future, TRAF4 may become one molecular marker for therapy of breast cancer." (PMID 25738361, 2015). "Interestingly, two recent reports showed that TRAF4 favors breast cancer cell migration." (PMID 24311986, 2013). "Interestingly TRAF4 overexpression is not limited to breast cancers." (PMID 24212830, 2011). "Interestingly, in breast cancers, TRAF4 amplification can occur independently of ErbB2 amplification suggesting that TRAF4 may be the target of a more centromeric amplicon than the one involving ErbB2." (PMID 24212830, 2011). "TRAF4, a vital member of the TRAF family, was initially identified as a differential gene highly expressed in breast cancer." (PMID 36765039, 2023). "In addition, TRAF4 could reduce the growth inhibitory effect of etoposide by reducing the number of S-phase cells in breast cancer cells and inhibiting apoptosis, which may be the reason for the poor chemotherapy efficiency in patients with breast cancer with high TRAF4 expression." (PMID 36765039, 2023). "While TRAF4 was overexpressed in almost all subtypes of breast cancer, the overexpression was more prominent in HER2+/HR− breast cancer samples compared to HER2−/HR+ and TN breast cancer samples." (PMID 35864174, 2022). "TRAF4 interacts with p70s6k in MCF7 and MDA-MB-231, leading to the proliferation of breast cancer cells." (PMID 35242717, 2022). "High grade invasive ductal carcinoma (IDC) had significantly higher copy numbers of HER2 gene and TRAF4 gene than low/medium grade IDC, suggesting that TRAF4 and HER2 are synchronized in the progression of breast cancer infiltration." (PMID 35242717, 2022).
breast carcinoma (continued). "Following the discovery of functional interdependence between TRAF4, SMURF2 and HER2, we subsequently evaluated the endogenous physical interaction among TRAF4/SMURF2/HER2 in HER2+ breast cancer cell lines." (PMID 35864174, 2022). "TRAF4, an important member of the TRAF family, was initially identified as a highly expressed differential gene in breast cancer." (PMID 36077559, 2022). "It has been reported that TRAF4 can enhance the nuclear protein level of PRMT5 in breast cancer cells, thereby promoting the proliferation of breast cancer cells." (PMID 35692762, 2022). "TRAF4 regulates the TGF-β pathway, promotes TGF-β receptor signaling, and drives breast cancer metastasis." (PMID 35242717, 2022). "Knockdown and knockout of TRAF4 dramatically reduced both the stability of HER2 receptor and the activation of HER2 downstream signaling pathways, improving sensitivity of breast cancer cells and PDX-derived organoids to Trastuzumab treatment." (PMID 35864174, 2022). "In estrogen receptor-positive breast cancer cells (MCF-7), TRAF4 expression was higher in the nucleus than in estrogen receptor-negative breast cancer cells (MDA-MB231), with the opposite expression in the cytoplasm." (PMID 35242717, 2022). "Here we identified TRAF4 overexpression as one of the putative mechanisms for HER2-positive breast cancer cells to maintain HER2 signaling during Trastuzumab treatment, while TRAF4 knockdown reduced HER2 stability and improved Trastuzumab sensitivity." (PMID 35864174, 2022). "TRAF4 is required for effective TGF-β-induced migration, epithelial-mesenchymal transition, and breast cancer metastasis." (PMID 35242717, 2022). "TRAF4, known initially as CART1, is specifically expressed in breast cancer and localized in the nucleus in such tissues." (PMID 35242717, 2022). "TRAF4 expression correlated with phosphorylated SMAD2 and phosphorylated TGFβ activated kinase (TAK-1) and poor prognosis in breast cancer patients." (PMID 33418880, 2021). "In breast cancer cells, USP15 is recruited to TβRI with the assistance of TRAF4, a E3 ubiquitin ligase that also blocks SMURF2 inhibitory effects towards TGF-β pathway via degradation." (PMID 34575114, 2021). "TRAF4, the unique member of the TRAF family, has been studied for several decades since it was first identified in breast cancer." (PMID 25738361, 2015). "Following TGFβ ligand stimulation in breast cancer cells, SMURF2 is degraded in a TRAF4-dependent manner that facilitates recruitment of USP15 to TGFβ receptor I to sustain TGFβ signaling." (PMID 25606592, 2014). "In the current study, following TNF-α treatment in breast cancer MCF-7 cells, the expression of TRAF4 suppressed the activation of NF-κB and promoted early cell apoptosis." (PMID 24396457, 2014). "TRAF4 is thus required for efficient TGFβ-induced migration, EMT and breast cancer metastasis in a USP15-regulated fashion." (PMID 25606592, 2014). "The expression of TRAF4 in normal MCF-10A breast cells was found to be lower than in MCF-7 and MDA-MB-231 breast cancer cells." (PMID 24396457, 2014). "In unsupervised hierarchical clustering a distinctive group of male breast cancer with poor prognosis (p = 0.009; hazard ratio 3.4) was identified, characterized by frequent CCND1, MTDH, CDC6, ADAM9, TRAF4 and MYC copy number gain." (PMID 22527098, 2012). "Gene copy number gain of CCND1, TRAF4, CDC6 and MTDH was seen in >40 % of the male breast cancer cases, with also frequent amplification." (PMID 22527098, 2012). "In conclusion, copy number gain of the genes CCND1 (11q13), TRAF4 (17q11), CDC6 (17q21), and MTDH (8q22) is very common in male breast cancer (>40 %) and these genes probably play a role in male breast carcinogenesis." (PMID 22527098, 2012).
breast carcinoma (continued). "Two genes, TRAF4 (p = 0.024) and EMSY (p = 0.041) were more often amplified in female breast cancer." (PMID 22527098, 2012). "Compared to female breast cancer CCND1 and EGFR were found to be more frequently amplified in male breast cancer, while in females EMSY and CPD were more often involved and more frequent amplifications of TRAF4 and EMSY were found." (PMID 22527098, 2012). "For instance, TRAF4 has been reported to mediate IRS1 ubiquitination, regulating IRS1 binding with IGF-1R and subsequent IRS1 phosphorylation, leading to the stimulation of proliferation in breast cancer cells." (PMID 38272982, 2024). "mean difference − 4.15, 95% CI − 6.06, − 2.24, Z score 4.25 (P < 0.0001)) is associated with significant reduction in tumour weight and volume in female rodents bearing the human triple-negative MDA-MB-231 (TRAF2, TRAF4 and TRAF6) and mouse 4T1 (TRAF6) breast cancer cells." (PMID 36944688, 2023). "In conclusion, we discovered a new HER2 signaling regulation that involves the TRAF4-SMURF2 complex, a possible mechanism that might contribute to anti-HER2 resistance, making TRAF4 a viable target for treating HER2 + breast cancer." (PMID 35864174, 2022). "Although a previous research has reported that SMURF1 can ubiquitinate HER2 when triggered by a compound JAC1, SMURF1 targeted by TRAF4 has not been validated, whereas SMURF2 has been shown to be targeted by TRAF4 for promoting TGF-beta signaling and facilitating breast cancer metastasis." (PMID 35864174, 2022). "For example, TRAF4 has been reported to be involved in the TRAF4-AKT/NF-κB-Glut1/HK2/RSK4/Slug pathway, which regulates the proliferation, migration and EMT of various cancer cells, such as lung and breast cancer." (PMID 34983361, 2022). "And TRAF4 expression was higher in estrogen receptor-positive breast cancer cell lines than in estrogen receptor-negative breast cancer cell lines." (PMID 35242717, 2022). "The results showed that TRAF4 over-protein level promoted MCF-7 and MDA-MB-231 cells proliferation, while co-transfecting TRAF4 plasmid and Eg5 si-RNA significantly reduced the TRAF4-induced proliferation of breast cancer cells." (PMID 35692762, 2022). "Moreover, TRAF4 and HER2 were shown to be co-expressed to some level in HER2+ breast cancer samples (r = 0.3189, p value < 0.0001)." (PMID 35864174, 2022). "In order to confirm the role of TRAF4 and Eg5 in the development of breast cancer in vivo, we transplanted breast tumours developed from MCF-7 cells, which were stably transfected with empty plasmid or TRAF4 overexpressed pasmid or both TRAF4 overexpressed pasmid and Eg5 sh-RNAs into nude mice." (PMID 35692762, 2022). "A previous study showed that TRAF4 promoted the degradation of SMAD ubiquitination regulatory factor 2 (SMURF2) by increasing the polyubiquitination of SMURF2 to regulate pro-oncogenic TGF-β signaling and promote breast cancer metastasis." (PMID 36535926, 2022). "To confirm that this interaction also occurred in breast cancer cells, we firstly investigated the location of TRAF4 and Eg5 in MDA-MB-231, SK-BR-3, MCF-7 and MDA-MB-453 breast cancer cells, and found both TRAF4 and Eg5 have cytoplasmic localization in these cells." (PMID 35692762, 2022). "However, HER2 expression was low in the MDA-MB-453 and ZR-75-1 cell lines, despite high TRAF4 expression, indicating that other mechanisms regulating HER2/TRAF4 existed in some breast cancer cell lines." (PMID 35864174, 2022). "In order to identify whether the expression of TRAF4 correlates with the activation of p70s6k in vivo, we detected the expression of TRAF4 and p-p70s6k (T389) in normal breast tissue(NBT) (n = 16) and breast cancer tissue (BCT) (n = 80)." (PMID 25738361, 2015).
breast carcinoma (continued). "Together with the previously established role of TRAF4 in binding to the C terminal juxtamembrane region of HER1(EGFR) and participating in EGFR signaling activation, our findings further support the oncogenic roles of TRAF4 in breast cancer through increasing the HER2 signaling pathways." (PMID 35864174, 2022). "In addition, we detected the expression of TRAF4 and p-p70s6k/p-S6 in breast cancer cells MCF7 and MDA-MB-231 along with non-malignant breast epithelial cells MCF10A by Western blotting." (PMID 25738361, 2015). "Interestingly, TRAF4 overexpression is not restricted to breast cancer and extends to a variety of different carcinomas." (PMID 24311986, 2013). "When we compared Eg5 and TRAF4 protein level in a non-malignant breast epithelial cell line (MCF-10A) and in breast cancer cell lines (MDA-MB-231, SK-BR-3, MCF-7and MDA-MB-453), we obtained a similar result." (PMID 35692762, 2022). "TRAF4 can promote both SMAD and non-SMAD signaling downstream of TβRI, during breast cancer progression, and was found to play an important role in mediating TGFβ-induced EMT and metastasis in breast cancer." (PMID 33418880, 2021). "Recently, TRAF4 was reported to activate TGF-β signaling and transduce both SMAD and non-SMAD pathways to promote breast cancer development." (PMID 28827764, 2017). "Next, the expression of TRAF4 was examined in normal MCF-10A breast cells and the estrogen receptor-positive and -negative breast cancer cell lines, MCF-7 and MDA-MB-231, respectively, by western blotting." (PMID 24396457, 2014). "TRAIL, TRAILR1, TRAF4, CASP10, and APAF1 increase upon Sin3A knockdown in MCF7, but not MDA-MB-231, breast cancer cells." (PMID 20920219, 2010).